ADK (adenosine kinase)
Description:
Adenosine kinase that mediates the phosphorylation of the purine nucleoside adenosine at the 5' position in an ATP-dependent manner: catalyzes phosphorylation of both unmodified and modified adenosines. Plays a key role in the detoxification of modified adenosines containing N(6)-methylated adenine (m6A) post-transcriptional modification. Modified nucleosides are derived from the degradation of RNAs (mRNAs, rRNAs and tRNAs) and possess intrinsic cytotoxicity and must be cleared to prevent metabolic dysfunction. Catalyzes the phosphorylation of the free cytosolic methylated adenosine nucleotides N(6)-methyladenosine (m6A), N(6),N(6)-dimethyladenosine (m6,6A) and N(6)- isopentenyladenosine (i6A) into adenosine monophosphate (AMP) intermediates that are further detoxified by MAPDA/ADAL.
Synonyms: AK
Tractability: Small molecule: a structure with a bound ligand is known; a high-quality ligand is known; it has a high-quality binding pocket; it belongs to a druggable protein family. Antibody: its Gene Ontology location is reachable by antibodies, with high confidence. PROTAC: ubiquitination databases record sites on it; its protein half-life has been measured; a small molecule that binds it is known.
Target class: Enzyme; Transferase
Chemical probes: NSC 113939
Gene: Protein-coding gene on chromosome 10 (74,151,191 to 74,709,963, forward strand). Ensembl gene ENSG00000156110.
Subcellular location: Cytoplasm, cytosol; Nucleus (Isoform 1); Cytoplasm (Isoform 2)
Subcellular location (Human Protein Atlas): Cytosol; Nucleoplasm; Plasma membrane
Pathways (Reactome):
Drug ADME: Ribavirin ADME
Metabolism: Purine salvage
Gene Ontology:
Molecular function: adenosine kinase activity; RNA binding; deoxyadenosine kinase activity; kinase activity
Biological process: purine nucleobase metabolic process; toxic metabolite repair; ribonucleoside monophosphate biosynthetic process; AMP salvage; dAMP biosynthetic process; GMP salvage; purine nucleotide salvage; purine ribonucleoside salvage
Cellular component: cytoplasm; cytosol; nucleoplasm; nucleus
Genetic constraint (gnomAD): Loss-of-function variants: 19 observed, 31.24 expected, observed/expected ratio (o/e) 0.61, 90% interval 0.42 to 0.89. The upper end of that interval is the gene's LOEUF score, 0.89, which puts it in group 3 of 6, group 1 being the genes least tolerant of losing a copy. Missense variants: 275 observed, 365.02 expected, observed/expected ratio (o/e) 0.75, 90% interval 0.68 to 0.83. Synonymous variants: 112 observed, 123.69 expected, observed/expected ratio (o/e) 0.91, 90% interval 0.78 to 1.06.
Gene-disease validity (ClinGen):
ClinGen rates the evidence that ADK causes each of these diseases.
adenosine kinase deficiency (autosomal recessive): Definitive.
Homologues: Orthologues: chimpanzee ADK (99% identical), rabbit ADK (98% identical), macaque ADK (97% identical), pig ADK (95% identical), mouse Adk (91% identical), guinea pig ADK (91% identical), dog ADK (89% identical), rat Adk (87% identical), zebrafish adka (78% identical), zebrafish adkb (75% identical), Drosophila melanogaster Adk2 (50% identical), Caenorhabditis elegans adk-1 (49% identical), and 1 more. Paralogues in human: RBKS (17% identical), KHK (14% identical), TMEM256 (3% identical).
Diseases named in the same sentence as ADK in open-access papers:
ADK is named in the same sentence as 93 diseases in open-access papers, as found by Europe PMC text mining. Sharing a sentence is not in itself a finding about the gene and the disease. The quoted sentences say what the papers report.
epilepsy (36 papers, 2009 to 2026). A brain disorder characterized by episodes of abnormally increased neuronal discharge resulting in transient episodes of sensory or motor neurological dysfunction, or psychic dysfunction. "(iv) Adenosine kinase (ADK) is highlighted as a pathological hallmark of epilepsy, with its distinct isoforms driving different mechanisms." (PMID 41897388, 2026). "Genes encoding glial proteins, for example, adenosine kinase, are also considered to be potential targets for epilepsy gene therapy." (PMID 39937026, 2025). "On the contrary, overexpression of ADK and adenosine deficiency can lead to nervous system pathology, in particular, to the development of epilepsy because adenosine acts as an inhibitory neuromodulator for neuronal cells and has an anticonvulsant effect." (PMID 35327609, 2022). "For example, increased ADK expression can enhance neuronal excitability, while decreased ADK expression is associated with epilepsy and brain injury." (PMID 35893077, 2022). "While dynamic regulation of ADK gene expression is important to early postnatal brain development, loss or inhibition of ADK promotes pathologies in the brain, e.g., cancer and epilepsy." (PMID 31623231, 2019). "ADK mutations or alterations in ADK expression have been involved in several pathologies including neurodevelopmental delay, epilepsy and gliomas." (PMID 30441833, 2018). "MSC were also modified by microRNA encoding sequences targeting adenosine kinase (ADK) in a background of epilepsy, providing evidence that an ADK knockdown in human MSC reduces acute injury and seizures when injected into mouse hippocampus." (PMID 26265166, 2015). "Transient down-regulation of ADK after acute brain injury protects the brain from seizures and cell death, while chronic ADK overexpression causes seizures in epilepsy and promotes cell death in epilepsy and stroke." (PMID 23667485, 2013). "Upregulation of ADK has been highly regarded as a common pathologic hallmark of epilepsy." (PMID 37017409, 2023). "ADK-deficient patients presented with liver dysfunction (most commonly with prolonged neonatal cholestatic jaundice), delayed psychomotor development, and neurological features including generalized hypotonia and epilepsy." (PMID 36589157, 2022). "Conversely, our patient did not present with epilepsy during 12 years of life, and thus we could conclude that epilepsy could be a variable feature of ADK deficiency." (PMID 36589157, 2022). "Mutations of ADK or modification of ADK levels have been associated with several diseases, such as stroke, Rasmussen encephalitis, focal cortical dysplasia, epilepsy and gliomas, as well as in cognition deficits." (PMID 34054547, 2021). "Dysregulation of ADK may be causative in some forms of epilepsy." (PMID 31496935, 2019). "Therefore, changes in adenosine metabolism, such as those triggered by pathological hyperexpression of ADK or by genetic mutations, could be biomarkers for epileptogenesis and also therapeutic targets to prevent epilepsy." (PMID 30441833, 2018). "Together these findings support an important role of adenosine in epilepsy and indicate the potential of ADK-targeting and adenosine-enhancing therapies for the treatment of the disease." (PMID 36244037, 2023). "As mentioned in the previous section, dysregulation of adenosine homeostasis due to overexpression of the key adenosine-metabolizing enzyme ADK leads to exacerbation of epilepsy and a general response to astrocyte activation." (PMID 37583518, 2023). "As adenosine exerts powerful anticonvulsive and neuroprotective effects by acting on pre- or postsynaptic A1 receptors, alterations in ADK expression are thought to play a crucial role in epilepsy." (PMID 36244037, 2023). "A recent review of ADK summarized its epigenetic effects in neurodevelopmental disorders, brain injury, and epilepsy." (PMID 35893077, 2022).
epilepsy (continued). "This suggests an epilepsy-induced compensatory increase of ADK in the NTS of WTs whereas Adk+/-mice were devoid of this change." (PMID 35754505, 2022). "The overexpression of ADK was demonstrated under different conditions of acute brain injury after the latent phase preceding the development of epilepsy." (PMID 35269653, 2022). "Primarily, ADK is a therapeutic target for conditions such as epilepsy, pain syndrome, and inflammation." (PMID 35327609, 2022). "Theofilas and colleagues used a similar approach to investigate the role of ADK in the pathogenesis of epilepsy." (PMID 35625877, 2022). "In the human temporal lobe with epilepsy and in the hippocampus and cortex of rodent models with epilepsy, ADK was found to be overexpressed in reactive astrocytes." (PMID 34635103, 2021). "Based on adenosine’s role as a product of DNA methylation, an increase in ADK and the resulting decrease in adenosine, as seen in epilepsy, drives increased global DNA methylation in the brain." (PMID 34144123, 2021). "An example of a local cell therapy approach to treat seizures in modelled epilepsy is based on lentiviral RNAi-mediated downregulation of ADK." (PMID 34144123, 2021). "Proof-of-concept studies of several ADK inhibitors have been carried out successfully in animal models of epilepsy." (PMID 34635103, 2021). "Decrease of adenosine is observed in several pathological conditions, as in epilepsy, in which ADK is increased." (PMID 34054547, 2021). "A novel treatment methodology has been successfully developed in which the transient use of a small-molecule ADK inhibitor during the critical stage of epileptogenesis provides disease-modifying effects against epilepsy in animals." (PMID 34635103, 2021). "Given that an elevation of extracellular adenosine produces beneficial effects on seizure control, the development of ADK inhibitors seems to a feasible way for the treatment of epilepsy." (PMID 33390891, 2020). "Using lentivirus, adeno-associated virus, and herpes simplex viral vectors in animal models, the most gene therapies for treatment of epilepsy targeted neurotrophic factors, galanin, adenosine kinase, and neuropeptide Y." (PMID 32440322, 2020). "ADK inhibitors were previously considered in pre-clinical models for a wide variety of conditions including epilepsy, pain, and chronic inflammatory diseases such as rheumatoid arthritis." (PMID 33324223, 2020). "The increased activity of ADK reduces the content of adenosine in synapses and promotes the development of epilepsy." (PMID 31334608, 2019). "When traumaor epilepsy happens, adenosine, as a modulator ofinflammation increases and induces proliferation ofastrocytes via A2ARs, leading to astrocyte activationand ADK overexpression." (PMID 29308612, 2018). "The astroglial expression of adenosine kinase (ADK) is elevated in the setting of epilepsy." (PMID 40429323, 2025). "Nevertheless, whether genetic ADK knockdown can yield possible preconditioning effects against the development of epilepsy warrants additional evaluation." (PMID 35754505, 2022). "In addition to ENT1, the role of ADK (a key adenosine-metabolizing enzyme) in the pathogenesis of epilepsy has been extensively explored in recent years." (PMID 34635103, 2021). "Because ADK progressively increases in line with epilepsy development and progression, and because epileptogenic activity originates from ADK-expressing brain areas, ADK is a biomarker to identify epileptogenic brain areas and to monitor epileptogenesis longitudinally." (PMID 34144123, 2021). "Unfortunately, the first line of ADK inhibitors showed liver toxicity side effects, but recently efforts have been made to develop novel ADK inhibitors which may present a viable therapeutic strategy for epilepsy in the future." (PMID 33324329, 2020).
epilepsy (continued). "Fourteen epilepsy-associated genes were identified as potential targets of ADORA2A in epilepsy, and four key genes including NT5E, ENTPD1, ADA, and ADK were mainly involved in the “negative regulation of neuron death” and “purine nucleoside biosynthetic process” biological processes." (PMID 33262686, 2020). "ADK inhibitors have since been developed and tested in animal models of epilepsy." (PMID 33324329, 2020). "The ADK hypothesis of epilepsy posits that acute insults to the brain lead to an initial and transient downregulation of ADK and an acute elevation of ADOe that is protective in the short term." (PMID 31496935, 2019). "Inhibiting ADK is expected to reveal new measures to prevent epilepsy." (PMID 31334608, 2019). "Transgenic mice with ADK knockout or hyperexpressing ADK through all the brain or in specific regions have been a useful tool to uncover the role of ADK in synaptic plasticity, learning, and epilepsy." (PMID 30441833, 2018). "Manipulated WJMSCs by Adeno, AAV, non-integrated lentiviral, CRISPR/Cas9 and RNA transferinstead of lentivirus, might be a suitable source in cell-based and ex vivo gene therapy of epilepsy and could beevaluated for ADK knockdown, in vivo." (PMID 29308612, 2018). "Since therapeutic adenosine augmentation restores normal DNA methylation levels and prevents epilepsy progression long-term increased ADK and increased DNA methylation status might form a vicious cycle implicated in the progression and maintenance of epilepsy." (PMID 27147960, 2016). "Based on these findings, it has been suggested that ADK is a therapeutic target for epilepsy and stroke and that Itu might be a potential drug to treat these disorders." (PMID 23667485, 2013). "Interestingly, ADK expression depends on the stage of epilepsy, with decreased expression immediately following intrahippocampal kainate injection, but increased expression during the latent or chronic periods (≥ 3 d) of epilepsy." (PMID 36244037, 2023). "The current focus of gene therapy strategies for epilepsy is primarily aimed at reducing neuronal excitability by overexpressing neuro-modulatory peptides such as neuropeptide Y, galanin etc. or by the genetic modification of astrocytes, for example, to suppress adenosine kinase (ADK) expression." (PMID 35645733, 2022). "Therefore, modulation of ADK expression is of interest in the context of epilepsy." (PMID 33324329, 2020). "Therefore, adenosine inhibits the pathogenesis of epilepsy through astrocytes, ADK, glutamate, epigenetic gene modification, the gamma‐aminobutyric acid receptor and other pathways, which will provide new ideas and measures for the treatment of epilepsy." (PMID 31334608, 2019). "Therefore, it appears that increased ADA and ADK may reduce adenosine levels, decrease its inhibitory activity and lead to epileptogenesis and progression of epilepsy in glioma patients." (PMID 30441833, 2018). "Therefore, tight regulation of ADK expression and activity becomes a necessity and it is not surprising that several pathologies such as epilepsy, diabetes or cancer are linked to ADK dysfunction." (PMID 27812320, 2016). "Inhibition of ADK strengthens A1AR activation and has a protective effect in ischemia, epilepsy and glutamate excitotoxicity." (PMID 34054547, 2021). "In this review, we describe the contribution of 5’-nucleotidases, ADK, ADA, AMPD and nucleoside transporters in epilepsy, cognition, and neurodegenerative diseases with a particular attention on serious pathological conditions such as ALS and HD." (PMID 34054547, 2021). "ADA and ADK, identified as key target genes of ADORA2A on epilepsy, are involved in glioma progression, and their upregulated expression in peritumoral tissues is associated with epilepsy in glioma patients." (PMID 33262686, 2020).
epilepsy (continued). "Pharmacological inhibition of ADK, or ADO augmentation therapies developed to inhibit ADK and raise ADOe greatly reduce seizures in animal models of epilepsy, whereas transgenic overexpression of ADK triggers seizures." (PMID 31496935, 2019). "Not surprisingly, ADK dysfunction is involved in several pathologies, including diabetes, epilepsy, and cancer." (PMID 27812320, 2016). "Inhibitors of ADK such as 4-(N-phenylamino)-5-phenyl-7-(5-deoxyribofuranosyl)pyrrolo[2,3-day]pyrimidine (GP683) and ABT-702 were primarily developed for chronic treatment paradigms such as for neuropathic pain and epilepsy and were abandoned due to toxicity in long-term usage." (PMID 33324223, 2020). "The unaltered expression levels of ADK, Cx43, and P2X7 receptors which contribute to the development of epilepsy together with the finding that astrogliosis per se without overexpression of ADK is insufficient to trigger SRS are consistent with the lack of SRS in our ELS mice." (PMID 39024558, 2024). "These indicate an epilepsy-induced adaptive A2AR increase in the NTS of both genotypes, regardless of ADK levels." (PMID 35754505, 2022). "ADA and ADK expression was upregulated in peritumoral tissues derived from patients with epilepsy compared to those without epilepsy, whereas the number of ADA-positive or ADK-positive cells in tumor tissues was similar between glioma patients with and without epilepsy." (PMID 30441833, 2018).